CYLD (CYLD lysine 63 deubiquitinase)
Diseases named in the same sentence as CYLD in open-access papers (continued):
Sharing a sentence is not in itself a finding about the gene and the disease.
adult T-cell leukemia/lymphoma (7 papers, 2020 to 2025). A peripheral (mature) T-cell neoplasm linked to the human T-cell leukemia virus type 1 (HTLV-1), adult T-cell leukemia/lymphoma is endemic in several regions of the world, in particular Japan, the Caribbean, and parts of Central Africa. "Inactivation of CYLD leads to a poor prognosis in marginal zone lymphoma, whereas, increased expression of CYLD is found in adult T-cell lymphoma." (PMID 40896706, 2025). "CYLD anomalies are also detected in adult T-cell leukemia/lymphoma (ATLL) cells, as hyper-phosphorylated CYLD losses its function of removing the ubiquitin chains on RIP1, leading to continuous activation of the NF-κB pathway." (PMID 34454635, 2021). "Our previous study indicated high protein expression levels of CYLD phosphorylation in adult T-cell leukemia/lymphoma (ATLL) and regulating CYLD phosphorylation could regulate CYLD ubiquitin activity to improve ATLL cells apoptosis." (PMID 33827598, 2021). "Our previous research has demonstrated that adult T-cell leukemia/lymphoma (ATLL) had high level of CYLD phosphorylation, down-regulating CYLD phosphorylation could increase CYLD deubiquitinase activity and then promoted apoptosis in ATLL." (PMID 33827598, 2021). "A recent study showed that CYLD phosphorylation is elevated in transformed cells and inhibition of this phosphorylation by IKK inhibitors triggers apoptosis, suggesting CYLD as a novel therapeutic target for adult T-cell leukemia." (PMID 32512887, 2020). "Phosphorylation of CYLD by IKKε promotes cell transformation by increasing NF-κB activation, but the presence of the IKK inhibitors leads to apoptosis indicating that CYLD may be a novel therapeutic target for adult T-cell leukemia." (PMID 32512887, 2020). "Additionally, in primary adult T-cell leukemia/lymphoma (ATLL) samples and cell lines, increased IKK-induced CYLD phosphorylation was observed." (PMID 34177595, 2021).
colon carcinoma (7 papers, 2010 to 2021). "To address the myeloid cell-specific role of CYLD in inflammation-associated colon cancer, we induced colon carcinogenesis in CYLDΔ932mye mice by a single injection of the alkylating agent AOM followed by repeated cycles of inflammation induced by oral administration of DSS25." (PMID 27561390, 2016). "For example, in colon cancer, miR-181b was able to target CYLD to inhibit the NF-κB signaling pathway 60, while, in cervical cancer, miR-501 can target CYLD to regulate cell proliferation, migration and invasion." (PMID 34326699, 2021). "A few USPs, such as CYLD, are characterized as tumor suppressor factors that inhibit the occurrence or metastasis of liver, skin, and colon cancers." (PMID 33619866, 2021). "The hsa-miR-181 family has been shown to be deregulated also in other solid tumours such pancreas, prostate, gastric and colon cancers and was able to target tumour suppressors, including TIMP3, CYLD, PTEN and p27." (PMID 26672991, 2015). "Analysis of THP1 human monocytic cells or HCT-116 human colon carcinoma cells, which both express NOD2 endogenously, confirmed that CYLD was not involved in controlling Met1-Ub accumulation on HOIP whereas OTULIN was indispensable." (PMID 26997266, 2016).
prostate carcinoma (7 papers, 2016 to 2024). A carcinoma that arises from epithelial cells of the prostate gland. "Module 2 includes TGFBR3, FOXO1, RSPO3, PLAG1, and CYLD, which have been shown to play a role in mediating or inhibiting prostate cancer progression." (PMID 39347576, 2024). "In prostate cancer cell lines, the knockout of CYLD increased the proliferation, migration, colony formation, and invasion of cancer cells in vitro." (PMID 35991559, 2022). "In prostate cancer, CYLD regulated ferroptosis through Hippo/YAP signalling." (PMID 38812041, 2024).
thymic carcinoma (7 papers, 2021 to 2023). Thymic carcinoma (TC) is a type of thymic epithelial neoplasm characterized by a high malignant potential. "In thymic carcinoma, pathogenic CYLD variants were associated with increased PD-L1 (CD274) levels and better response to immune checkpoint inhibitor therapy." (PMID 37387450, 2023). "CYLD mutations are linked to high PD-L1 expression in thymic carcinoma, and the downregulation of CYLD is associated with PD-L1 expression mediated by interferon-gamma in thymic epithelial tumor cell lines." (PMID 38201593, 2023). "The prevalence of CYLD gene mutations in thymic carcinomas exceeds 10%." (PMID 37849766, 2023). "Our whole-exome sequencing results also showed that CYLD were recurrently mutated in our cohort, indicating that pembrolizumab may be a potential ICIs for patients with thymic carcinoma." (PMID 34867976, 2021). "More recently, recurrent mutations in CYLD, predominantly whole-gene deletions and nonsense or frameshift mutations, have been identified in head and neck squamous cell carcinoma (21% of cases), thymic carcinoma (10% of cases) and anal carcinoma (13% of cases)." (PMID 37387450, 2023). "A trend for the absence of co-occurrence with GTF2I was observed also for CDKN2A, BAP1, CYLD, and KIT mutations, which are genes frequently mutated in B3 thymomas and thymic carcinomas." (PMID 37671056, 2023).
amyotrophic lateral sclerosis (6 papers, 2020 to 2025). Amyotrophic lateral sclerosis (ALS) is a neurodegenerative disease characterized by progressive muscular paralysis reflecting degeneration of motor neurons in the primary motor cortex, corticospinal tracts, brainstem and spinal cord. "Recent studies indicate that the human CYLD gene, which maps to chromosome 16q12.1, is a causative gene for frontotemporal dementia (FTD) and amyotrophic lateral sclerosis: patients carrying CYLD mutations (CYLD p.Met719Val) display prominent memory impairment." (PMID 36846565, 2023). "A seminal study from 2020 reported a novel mutation in the catalytic domain of CYLD (Met719Val) in an Australian family affected by amyotrophic lateral sclerosis-frontotemporal dementia (ALS-FTD)." (PMID 39945824, 2025). "Recently, a familial variant of CYLD with the M719V missense mutation was identified in the induction of frontotemporal dementia (FTD) and amyotrophic lateral sclerosis (ALS), with enhanced K63-deubiquitinating activity and NF-κB suppression." (PMID 32403254, 2020). "Our group has recently identified CYLD as a causal gene for FTD and amyotrophic lateral sclerosis (ALS), but it appears to be a relatively rare cause of the disease." (PMID 33802612, 2021).
frontotemporal dementia (6 papers, 2020 to 2025). Frontotemporal dementia (FTD) comprises a group of neurodegenerative disorders, characterized by progressive changes in behavior, executive dysfunction and language impairment, as a result of degeneration of the medial prefrontal and frontoinsular cortices. "An example of the importance of model selection is illustrated by the pathogenic variant M719V in CYLD, which is associated with frontotemporal dementia (FTD) in humans." (PMID 37387450, 2023). "The Cyld gene is involved in various neurological disorders, including anxiety, frontotemporal dementia, and ALS, and CYLD is widely distributed in the brain, with its highest expression level in the striatum." (PMID 37241833, 2023).
head and neck squamous cell carcinoma (6 papers, 2016 to 2022). A squamous cell carcinoma that arises from any of the following anatomic sites: lip and oral cavity, nasal cavity, paranasal sinuses, pharynx, larynx, and salivary glands. "al have identified a distinct subset of HPV-associated head and neck squamous cell carcinomas that have TRAF3/CYLD mutations." (PMID 31396277, 2019). "Mutation of CYLD in HPV-positive head and neck squamous cell carcinomas (HNSCCs) leads to the activation of NF-κB signaling and maintenance of episomal HPV in tumors." (PMID 31396277, 2019). "Defects in TRAF3/CYLD have been implicated in the activation of NF-κB signaling in HPV-positive head and neck squamous cell carcinoma (HNSCC) and EBV-positive NPC26,37, suggesting that TRAF3 and CYLD genetic alterations may also participate in EBV-mediated tumorigenesis in pulmonary LELC." (PMID 31311932, 2019).
nasopharyngeal carcinoma (6 papers, 2020 to 2024). A carcinoma arising from the nasopharyngeal epithelium. "For EBV+ nasopharyngeal carcinoma cells, somatic mutations have been found in the cellular DUB gene known as CYLD." (PMID 36802409, 2023). "Exceptions with more frequent TRAF3 and CYLD mutations include two virally-associated cancers, HPV+ HNSCC and Epstein-Barr virus-associated nasopharyngeal carcinoma (NPC)." (PMID 35634245, 2022). "A recent study reported that CYLD was downregulated in nasopharyngeal carcinoma and that CYLD overexpression promoted apoptosis by upregulating N-myc downstream regulated 1 (NDRG1)." (PMID 33919439, 2021). "Furthermore, CYLD mediates nasopharyngeal carcinoma cell radiosensitivity through class I HDACs." (PMID 38287022, 2024).
cervical cancer (5 papers, 2019 to 2025). A primary or metastatic malignant neoplasm involving the cervix. "Some studies have shown that CYLD can inhibit cancer cell proliferation, migration, invasion, and metastasis, and downregulated CYLD is associated with the development and progression of cervical cancer." (PMID 35435104, 2022). "Similarly, there have been previously conducted studies on the promoting role of miR-501 in cervical cancer, and results found that its up-regulation augmented the cell proliferation, migration and invasion of cervical cancer through the regulation of the target gene of CYLD." (PMID 31307515, 2019).
colitis (5 papers, 2014 to 2022). Inflammation of the colon. "Following Citrobacter rodentium infection, CYLD-deficient mice exhibit a substantially higher IL-18 concentration, indicating that severe mice colitis depends on elevated IL-18 production." (PMID 35145062, 2022). "Studies have revealed that CYLD-deficient mice are susceptible to colitis." (PMID 35145062, 2022). "In transferred T cell models, the loss of CYLD induces autoimmunity and colitis." (PMID 35145062, 2022). "In an azoxymethane and DSS-induced colitis-associated cancer model, CYLD-deficient mice are susceptible to colonic inflammation with histological damage, greater leucocyte infiltration, increased dysplastic changes and more mucosal ulcers in the intestinal epithelium." (PMID 35145062, 2022). "However, CYLD-deficient Treg cells were shown to be less functional, failing to inhibit colitis in an adoptive transfer colitis model." (PMID 28842469, 2017). "RNA interference based silencing (RNAi) of CYLD also results in activation of JNK signalling and Cyld deficient mice develop severe colonic inflammation, colitis-associated tumours, and hepatocellular carcinoma." (PMID 25565632, 2014). "CYLD inhibition protects epithelial cells from death and prevents commensal bacterial infection and intestinal epithelial barrier disruptions that trigger colitis development." (PMID 35145062, 2022). "CYLD−/− mice do not develop spontaneous tumors; however, they are highly susceptible to dextran sulfate sodium-induced colitis and azoxymethane-induced tumor development." (PMID 29259980, 2017). "Endoscopic and histological analyses of mice with an IEC-specific deficiency of FADD, an adaptor protein involved in apoptosis initiation, have revealed severe colitis with epithelial erosion, mucosal thickening and transmural inflammation that may be due to CYLD catalytic activity." (PMID 35145062, 2022). "Co-overexpression of CYLD splicing and SMAD7 in T cells impairs Treg cell suppressive functions, resulting in abnormal T cell homoeostasis and triggering fatal colitis." (PMID 35145062, 2022).
colorectal cancer (5 papers, 2021 to 2022). A primary or metastatic malignant neoplasm that affects the colon or rectum. "But in early-stage colorectal cancer CYLD protein expression levels were high and gradually decline with disease progression." (PMID 33827598, 2021). "A wide range of studies have shown that the expression of CYLD could be suppressed at transcription level by different non-coding RNAs, whereas whether CYLD abundance was repressed at post-transcription manner in colorectal cancer should be determined." (PMID 36185211, 2022).
glioblastoma (5 papers, 2014 to 2025). The most malignant astrocytic tumor (WHO grade IV). "On the other hand, in ovarian cancer cells and glioblastoma cells that show persistent NF-κB activity and high levels of TRIP6, both A20 and CYLD bind to TRAF6 very weakly." (PMID 27134758, 2016). "Although we found loss of CYLD expression in hypoxic regions of human glioblastoma multiforme (GBM), the most aggressive brain tumor, biological roles of CYLD in GBM remain unknown." (PMID 25071012, 2014).
head and neck cancer (5 papers, 2016 to 2023). A primary or metastatic malignant neoplasm affecting the head and neck. "Comprehensive genomic profiling via hybrid capture-based DNA sequencing was performed on 703 consecutive head and neck carcinomas with hrHPV sequences, identifying 148 unique cases (21%) harboring CYLD mutations." (PMID 32892208, 2021). "Interestingly, whole-exome sequencing (WES) studies of multiple cancer types also revealed CYLD mutations in many human malignancies, including head and neck cancers and several epithelial cancers." (PMID 31093340, 2016). "In comparison with HPV-related CYLD-wildtype head and neck carcinoma, CYLD-mutant cases were sequenced more frequently from liver samples (24% [35/148] vs. 7% [37/555], p < 0.0001)." (PMID 32892208, 2021). "Indeed, we found that experimental TRAF3 and CYLD inactivation was sufficient to strikingly sensitize HPV+ head and neck cancer cells to radiation, as well as promote increased expression of well-known NF-κB targets and sky blue (NF-κB) module genes." (PMID 37523561, 2023). "Importantly, activation of NF-κB via depletion of TRAF3 or CYLD resulted in elevated radiosensitivity of HPV+ head and neck cancer cells." (PMID 37523561, 2023). "In humans, CYLD mono-allelic mutations underlie cutaneous tumour predisposition syndromes and somatic CYLD mutations have been linked to human papillomavirus-associated head and neck cancer, whereas germline mutations in SPATA2 have not been described." (PMID 33473179, 2021). "Further understanding of the role of CYLD in head and neck epithelial biology may also identify mechanisms of tumorigenesis and progression of head and neck cancers, as well as other human malignancies." (PMID 31093340, 2016). "Interestingly, CYLD genetic aberrations have recently been reported by recent whole-exome sequencing (WES) studies in head and neck cancers, and some other cancers, thus revealing its potential involvement in human carcinogenesis." (PMID 31093340, 2016). "It is possible that CYLD alterations may be involved in the tumorigenesis of many other cancers, in addition to head and neck cancers." (PMID 31093340, 2016). "In our database, we identified 703 distinct hrHPV-positive head and neck carcinoma specimens, of which head and neck adenocarcinoma and cases of salivary gland origin were excluded as no HPV-positive CYLD-mutant cases were identified in these groups." (PMID 32892208, 2021).
leukemia (5 papers, 2021 to 2024). A malignant (clonal) hematologic disorder, involving hematopoietic stem cells and characterized by the presence of primitive or atypical myeloid or lymphoid cells in the bone marrow and the blood. "Since aberrant expression of CYLD is found frequently in leukemia, we ask whether there is a correlation between CYLD expression level and clinical outcomes." (PMID 37549179, 2023). "However, CYLD expression is repressed in T-ALL patient samples, and our data demonstrate that LCK is differentially regulated in the thymus compared to leukemia settings." (PMID 36490346, 2022).
liver cancer (5 papers, 2014 to 2025). An epithelial or non-epithelial malignant neoplasm that arises from the liver. "In liver cancer, tumor-associated neutrophils (TANs) stimulate miR-301b-3p to express, which subsequently inhibits the level of CYLD and LSAMP and upregulates chemokine (CXCL5), leading to a higher infiltration of TANs." (PMID 39525474, 2024). "Liver-specific deletion of "full-length" CYLD, accompanied by expression of an ablated CYLD splice variant, resulted in chronic liver injury and profoundly increased sensitivity towards carcinogen-induced liver cancer." (PMID 25329885, 2014). "We consider that it is enough for CysLTs/CysLTR2 signaling transduction to take a local or transient effect on inhibiting CYLD expression in liver cancer pathology." (PMID 35978827, 2022). "Our study illustrates reduced nuclear CYLD expression in liver cancer cell lines." (PMID 25329885, 2014). "Although CYLD has also been reported as a target of miR-362-5p in liver cancer, it was not identified in our predictions." (PMID 40406521, 2025). "In comparison, CYLD lysine 63 deubiquitinase (CYLD), the reported target gene of miR-362-5p, showed no significant changes at the mRNA level but decreased at the protein level in liver cancer tissues." (PMID 40083930, 2025).
acute lymphoblastic leukemia (4 papers, 2016 to 2022). Leukemia with an acute onset, characterized by the presence of lymphoblasts in the bone marrow and the peripheral blood. "Previous studies have revealed the role of miR-19/CYLD/NFKB and miR-429/MYCN/MFHAS1 FFLs in the development or relapse of T-lineage acute lymphoblastic leukemia (T-ALL)." (PMID 35805200, 2022). "In another study, interference with CYLD completely restored glucocorticoid resistance in children with acute lymphoblastic leukemia (ALL), suggesting that targeting CYLD may be a pharmacological approach to treatments for patients with refractory ALL." (PMID 29259980, 2017). "Proteolytic cleavage of CYLD through the para-caspase MALT-1 tissue results in NF-κB activation, which is a key step in the initiation of T-cell acute lymphoblastic leukemia (T-ALL)." (PMID 32354135, 2020).
Autoimmunity (4 papers, 2014 to 2024). The occurrence of an immune reaction against the organism's own cells or tissues. "Finally, it is apparently difficult to conceive that the absence of ubiquitin ligase or deubiquitinases such as A20 or CYLD, which have the opposite effect leads to autoimmunity." (PMID 24917867, 2014). "In addition to the EAE model in which CYLD overexpression in microglia did not confer protection against autoimmune neuroinflammation in R26-Cyld-OECx3 mice, we used a model of LPS-induced neuroinflammation to directly stimulate microglial inflammatory responses." (PMID 39302418, 2024).
benign skin tumors (4 papers, 2016 to 2024). "Brooke–Spiegler syndrome (BSS) is an autosomal dominant disease associated with the CYLD gene, which manifests itself as multiple benign skin tumors." (PMID 39403278, 2024). "The CYLD tumor suppressor gene encodes for a deubiquitinating enzyme involved in cylindromatosis syndrome, characterized by multiple skin benign tumors." (PMID 37749078, 2023). "Clinically, CYLD gene mutations manifest by multiple benign tumors of the skin and its appendages." (PMID 39403278, 2024).